RIPK1 (receptor interacting serine/threonine kinase 1)
Diseases named in the same sentence as RIPK1 in open-access papers (continued):
Sharing a sentence is not in itself a finding about the gene and the disease.
atherosclerosis (continued). "In atherosclerosis, elevated levels of RIPK1, RIPK3, and phosphorylated MLKL have been detected in unstable atherosclerotic plaques from humans and Ripk3-deficient mice develop significantly smaller advanced aortic atherosclerotic lesions." (PMID 34572045, 2021). "However, owing to the fact that RIPK1 plays roles in regulating necroptosis, apoptosis, autophagy, inflammation and cell survival pathways, it is difficult to speculate how the substantial decrease in RIPK1 affects atherosclerosis in Ripk3-deficient animals." (PMID 31953345, 2020). "Inhibition of RIPK3 or RIPK1 played a protective role from conditions such as atherosclerosis, renal ischemia reperfusion, and renal graft rejection." (PMID 29527209, 2018). "Furthermore, myeloid cell-specific deletion of RIPK1 limits plaque formation during the early phase of atherosclerosis activation." (PMID 40562870, 2025). "Thus, targeting RIPK1/3 and necroptosis is a promising therapeutic strategy for treating atherosclerosis at least in early stage." (PMID 39872161, 2022). "However, pharmacological inhibition of RIPK1 in ApoESA/SA mice, a model for investigating advanced atherosclerosis, only reduces plaque lesion in early stage, and promotes more atherosclerosis lesions in late stage." (PMID 39872161, 2022). "In another study, antisense oligonucleotides targeting receptor-interacting serine/threonine-protein kinase 1 (RIPK1) in ApoE−/− mice identified the inflammatory role of RIPK1 in atherosclerosis and suggested RIPK1 as a potential future therapeutic target to limit atherosclerotic inflammation." (PMID 36361754, 2022). "RIPK1 inhibition generates different results in the early and advanced stages of atherosclerosis." (PMID 35498045, 2022). "Similarly, in atherosclerosis and abdominal aortic aneurysms, inhibiting RIPK1/3 can reduce the formation of foam cells and the development of small aneurysms." (PMID 34867386, 2021). "RIPK1 is expressed in human and mouse atherosclerosis lesions, highly in macrophages." (PMID 34760938, 2021). "The role of RIPK1 in the development of advanced atherosclerosis, which features both inflammation and cell death, remains unclear." (PMID 34760938, 2021). "RIPK1 Inhibition is protective in myocardial infarction and early atherosclerosis in mice." (PMID 34760938, 2021). "The effects of treatment are intriguing and suggest that RIPK1 may potentially act to promote atherosclerosis through pathways beyond necroptosis." (PMID 33142926, 2020). "Additionally, studies indicate that RIPK1 may contribute to atherosclerosis by activating the NF-κB pathway and promoting inflammation." (PMID 39301029, 2024). "We elaborated on RIPK1/3-mediated necroptosis, pathways involved, the latest regulatory molecules and therapeutic targets in terms of ischemia reperfusion, myocardial remodeling, myocarditis, atherosclerosis, abdominal aortic aneurysm, and cardiovascular transplantation, etc." (PMID 34867386, 2021). "The role of RIPK1 in advanced-stage atherosclerosis is unknown." (PMID 34760938, 2021). "Meanwhile, the RIPK1/RIPK3/MLKL pathway-mediated necroptosis plays a significant role in various CVDs, including atherosclerosis, ischemia-reperfusion injury, myocardial infarction, and myocarditis." (PMID 39301029, 2024). "Two kinase proteins that play pivotal roles in the necroptosis pathway, receptor-interacting protein kinase 1 (RIPK1) and RIPK3, have emerged as the key proteins for their destructive role in atherosclerosis." (PMID 39227813, 2024). "At baseline (0 weeks WD), very low levels of RIPK1, RIPK3, and MLKL were observed in the atherosclerosis-prone aortic arch of both ApoE−/− and ApoE−/− Fbn1C1039G+/− mice but the expression levels increased during plaque progression." (PMID 35625752, 2022).
atherosclerosis (continued). "Taken together, these data suggest that RIPK1 inhibition might lead to the foam cell accumulation in the plaque both by promoting foam cell formation (via upregulating lipid uptake) and by suppressing their cell death, thus exacerbating late-stage atherosclerosis." (PMID 34760938, 2021). "In humans and preclinical models of disease, necroptosis has been shown to be activated in atherosclerotic plaques, and the damaging roles of RIPK1 and RIPK3 in atherosclerosis formation are beginning to come to light." (PMID 33142926, 2020). "Therefore, RIPK1 and RIPK3 are closely related to the onset and progression of atherosclerosis and inflammation‐mediated stroke." (PMID 39657719, 2024). "Additionally, we identified 4 new MMVD stage B2 targets (MDM2, ROCK1, RIPK1, and SNAP23) that have been studied in many cardiovascular diseases in human medicine, such as chronic heart failure, atherosclerosis, and diabetic cardiomyopathy." (PMID 38087280, 2023). "The DENRGs were particularly involved in necroptosis, lipids and atherosclerosis, TNF signaling pathway, legionellosis, cytosolic DNA-sensing pathway, RIPK1-mediated regulated necrosis, TRAIL signaling, Kaposi sarcoma-associated herpesvirus infection, and the NLRP3 inflammasome." (PMID 35991562, 2022). "Therefore, the mono-selective, new generation RIPK1 kinase inhibitor GSK’547 was included in the present study to treat atherosclerotic ApoE−/− Fbn1C1039G+/− mice, which is a model of advanced, human-like atherosclerosis." (PMID 35625752, 2022).
Stroke (22 papers, 2018 to 2025). Sudden impairment of blood flow to a part of the brain due to occlusion or rupture of an artery to the brain. "Next, several studies have revealed that multiple post-translational modification molecules, such as cylindromatosis (CYLD), chromatin immunoprecipitation (CHIP), Triad3A and ribosomal S6 kinase 3 (RSK3), have been implicated in stroke by mediating the activation of RIPK1 and RKPK3." (PMID 38026442, 2023). "Fasudil and the RIPK1 inhibitor necrostatin-1 were administered to modulate pericyte dysfunction and survival during the acute and subacute phases of stroke." (PMID 40540723, 2025). "Relevant experiments have shown that the RIPK1 inhibitor Nce-1 can alleviate pathological changes in a major cerebral artery occlusion model of stroke." (PMID 41142942, 2025). "Due to the dual role of RIPK1 on inflammation and of driving cell death, Nec-1 can also reduce cerebral apoptosis, oxidative stress, and inflammation in adult models of stroke and HI injuries." (PMID 36428481, 2022). "It has been widely reported that stroke leads to changes in the Gls and Ripk1 genes, which is consistent with the changes in the expression levels of Gls and Ripk1 in the brain on the second day after brain injury (B2B vs. BC)." (PMID 36605216, 2022). "Due to the dual role of RIPK1 on inflammation and cell death, Nec-1 is also able to reduce cerebral apoptosis, oxidative stress, and inflammation in adult models of stroke and HI injuries." (PMID 36428481, 2022). "Nec-1 is now widely used to block RIPK1 kinase activity in various experimental disease models, including stroke." (PMID 33629276, 2021). "Mice with a kinase dead RIPK1 mutant (Ripk1D138N/D138N) were found to have reduced stroke volume after 60 min of MCAO followed by 23 h of reperfusion compared to wild-type mice." (PMID 33142926, 2020). "Given that at its core, tissue ischemia, infarction, and cell death underlie ischemic stroke, the role of necroptosis, RIPK1, and RIPK3 in stroke has become a topic of interest." (PMID 33142926, 2020). "For example, stroke increases the levels of Ripk1, a necroptosis promotor, while transplanted medium and NSC oppose this process." (PMID 30394012, 2018). "And the results in this study demonstrated reduced stroke volume and improved neuronal deficits after stroke intervened by CasRx-Ripk1-Nsf, which suggested that advances in CRISPR/CasRx-mediated multi-gene therapy are paving the way for future therapeutic applications in ischemic stroke." (PMID 38919602, 2024). "This study may not only reveal the association of RIPK1 and RIPK3 with stroke severity and prognosis but also explore how these findings can be translated into clinical applications." (PMID 39657719, 2024). "Moreover, it has been shown that GSK3β interacts with RIPK1 molecules to promote RIPK1 molecular activity and promote post-stroke scar formation, leading to poor prognosis." (PMID 37443080, 2023). "Similarly, yet better characterized, necroptosis has been shown to be a promising drug target in PD, AD, and stroke, with RIPK1 inhibition alleviating brain damage in models of MS, AD, PD, and stroke." (PMID 35961983, 2022). "Ripk1 and Casp8 expression in the ipsilateral hemisphere followed the same pattern: they were significantly up-regulated by stroke (P < 0.01 for Ripk1 and P < 0.001 for Casp8) and reduced by NSC transplantation and the injection of proliferation-supporting medium to levels similar to healthy mice." (PMID 30394012, 2018). "This hypothesis posits that, during stroke, the pH of the extracellular solution falls, leading to a conformational change in the channel which exposes a binding site on the C-terminus for serine/threonine receptor interacting protein kinase 1 (RIPK1)." (PMID 38054969, 2023).
Stroke (continued). "In summary, we demonstrated that localized knockdown of Ripk1 mRNA and Nsf mRNA mediated by CRISPR-CasRx in the striatum and S1BF leads to a reduction in stroke size and an improvement in neurological deficits in a mouse model of tMCAO." (PMID 38919602, 2024). "The protein levels of RIPK1 MLKL and pMLKL are significantly increased in stroke tissues of both rats and human beings." (PMID 38026442, 2023). "For example, we showed that Casp8, Ripk1, and Ripk3 were up-regulated following stroke, although it has been shown that CASP8 blocks assembly of necroptotic complex composed of RIPK1 and RIPK3, leading the cell to apoptosis." (PMID 30394012, 2018). "Therefore, serum RIPK1 and RIPK3 levels can reflect the severity of inflammation expression and the severity of the condition after stroke." (PMID 39657719, 2024). "In addition, we propose new diagnostic methods, prognostic assessment tools, or treatment strategies based on RIPK1 and RIPK3 levels that have the potential to bring practical medical benefits to stroke patients." (PMID 39657719, 2024). "From this, it could be seen that serum RIPK1 and RIPK3 had high predictive value in the assessment of the condition and prognosis of stroke." (PMID 39657719, 2024). "In an experimental stroke model, independent of its ion-conducting function, ASIC1a was significantly induced and participated in the phosphorylation of RIPK1 by recruiting RIPK1 to the ASIC1a C-terminus (CT) and mediated RIPK1 activation." (PMID 38026442, 2023). "Interestingly, the levels of RIPK1 and RIPK3 are reduced after controlling post-traumatic body temperature at 33 °C to reduce brain injury after stroke and TBI." (PMID 36934132, 2023). "Although the role of RIPK1 and RIPK3 in the regulation of apoptotic signaling has been extensively studied, this study may delve deeper into the specific correlation between RIPK1 and RIPK3 and specific levels in the serum of stroke patients." (PMID 39657719, 2024). "Similar results were obtained in experimental stroke models; both Nec-1 and SB216763 (a glycogen synthase kinase-3 β inhibitor) attenuated ischemia-induced reactive astrogliosis by reducing the interaction between RIPK1 and glycogen synthase kinase 3β (GSK3β) and inhibiting inflammatory cytokines." (PMID 38026442, 2023).
glioma (20 papers, 2014 to 2025). A benign or malignant brain and spinal cord tumor that arises from glial cells (astrocytes, oligodendrocytes, ependymal cells). "In a cohort of 81 clinical glioma samples, high Ki67 labeling indices (30–80%) were associated with significantly elevated RIPK1 and MLKL expression compared to low-Ki67 tumors (<30%)." (PMID 41429922, 2025). "Collectively, these data highlight the association between necroptosis machinery and glioma aggressiveness, suggesting a pivotal role for RIPK1, RIPK3, and MLKL in disease progression and clinical outcome." (PMID 41429922, 2025). "The overexpression of RIPK1 was associated with a poor prognosis for DG, suggesting that RIPK1 plays a critical role in glioma pathogenesis and should be considered in therapeutic decision-making." (PMID 40565018, 2025). "The risk scores of glioma patients were calculated based on the coefficient and expression levels of each gene and the formula was as follows: risk score = 0.431 * RIPK1 +0.227 * RIPK3 + 0.302 * FAS +0.373 *FADD." (PMID 35719998, 2022). "Importantly, our findings link RIPK1 to glioma invasiveness, as its loss significantly reduces migratory and invasive capabilities and downregulates N-cadherin expression." (PMID 41429922, 2025). "Notably, RIPK1 appeared predominantly in its cleaved form across glioma samples, suggesting loss of its death-promoting activity and a shift toward pro-survival signaling." (PMID 41429922, 2025). "This may be consistent with the finding of a previous study that reported an association between RIPK1 overexpression and glioma progression." (PMID 36466844, 2022). "Together, these results establish RIPK1 as a central node coordinating both the proliferative and invasive phenotypes of glioma." (PMID 41429922, 2025). "Altogether, our results suggest that RIPK1 plays a crucial role in glioma progression and pathogenesis." (PMID 40565018, 2025). "Given the potential role of RIPK1 in glioma immunity due to its role in necroptosis and pyroptosis, we performed a meta-analysis using previously validated immune genetic signatures of tumor-infiltrating immune cells." (PMID 40565018, 2025). "A Cox proportional hazards model applied to 23 TCGA cancer cohorts identified RIPK1, RIPK3, and MLKL as significant risk factors for OS in WHO grade II and III gliomas." (PMID 41429922, 2025). "To define the molecular pathways underpinning RIPK1-dependent glioma invasiveness, we conducted RNA-seq analyses of wild-type versus RIPK1–/– U251 cells." (PMID 41429922, 2025). "Our data identify RIPK1 and MLKL as independent prognostic markers for glioma and reveal distinct roles for RIPK1 beyond its established function in necroptosis." (PMID 41429922, 2025). "Together, these results indicate that RIPK1 promotes glioma invasiveness by facilitating EMT and shaping the collagen-rich extracellular microenvironment." (PMID 41429922, 2025). "Consistently, RIPK1 knockout reduced N-cadherin expression, a hallmark of epithelial–mesenchymal transition (EMT) in glioma, while RIPK1 overexpression increased its expression, suggesting that RIPK1 promotes an EMT-like phenotype." (PMID 41429922, 2025). "In particular, the high-RIPK1 wtIDH gliomas showed an upregulation of macrophages, neutrophils, and memory T cells, while the Treg and NK cell gene signatures were significantly lower than those of the low-RIPK1 tumors." (PMID 40565018, 2025). "We found that the expression of genetic signatures of different lymphocyte populations, i.e., helper, cytotoxic, memory, and regulatory T cells, was upregulated in the mIDH gliomas with high RIPK1 expression levels." (PMID 40565018, 2025). "Elevated RIPK1 protein levels correlate with IDH1 wild-type status and increased Ki67 expression, aligning with its association with glioma aggressiveness and correspondingly demonstrating the highest HR for reduced OS." (PMID 41429922, 2025).
glioma (continued). "Here, we show that elevated expression of key necroptotic machinery proteins, including RIPK1 and MLKL, is positively associated with disease progression and predicts poor prognosis in glioma patients." (PMID 41429922, 2025). "RIPK1 depletion significantly reduced glioma cell proliferation, prompting an investigation into the role of its kinase activity." (PMID 41429922, 2025). "To investigate the role of the necroptotic machinery in glioma, we analyzed the mRNA expression profiles of RIPK1, RIPK3, and MLKL across normal brain and glioma samples." (PMID 41429922, 2025). "For the wtIDH gliomas, we observed that the expression of the genetic signatures of the macrophages and neutrophils was upregulated in the samples with high RIPK1 expression levels." (PMID 40565018, 2025). "Among the seven prognostic necroptosis genes, especially RIPK1, RIPK3, FAS and FADD, can construct risk profiles and predict the prognosis of glioma patients." (PMID 38304870, 2024). "Of the seven prognostic necroptosis genes, RIPK1, RIPK3, FAS, and FADD were used to construct the risk signature that accurately predicts the prognosis of glioma patients." (PMID 35719998, 2022). "In this direction, RIPK1 could play a role in sustaining inflammation through the regulation of proinflammatory death pathways collaborating with glioma pathogenesis." (PMID 40565018, 2025). "Treatment of U251 glioma cells with the RIPK1 kinase inhibitors Nec-1 or the MLKL oligomerization and membrane translocation inhibitor necrosulfonamide (NSA), respectively, had no significant impact on cellular growth, indicating that the pro-proliferative role of RIPK1 is kinase-independent." (PMID 41429922, 2025). "Notably, these effects occur independently of RIPK1’s kinase activity, highlighting its kinase-independent role in regulating glioma cell proliferation." (PMID 41429922, 2025). "However, we observed a significant decrease in the expression of genetic signatures of Tregs in the wtIDH gliomas with high RIPK1 expression levels." (PMID 40565018, 2025). "RIPK1 was positively correlated with the expression of cyclin E1 (CCNE1), CDK2, TIMP1, N-cadherin (CHD2), and other genes implicated in glioma proliferation and invasion, whereas MLKL exhibited a weaker or negative correlation with most genes in this signature." (PMID 41429922, 2025). "We observed an upregulation of programed necrosis-related proteins MLKL/RIPK3 and a concomitant downregulation of RIPK1 expression in glioma cell lines U251, U87, A172, and T98G, as well as in an in vivo subcutaneous tumor model, following Shikonin interventions." (PMID 39619148, 2024). "Two important examples are the plant-derived flavonoid, kaempferol, which leads to induction of autophagy and pyroptosis of glioma cells, and the plant-derived cytokine N6-isopentenyladenosine (iPA), which leads to activation of RIPK1, RIPK3, and MLDL, with subsequent induction of necroptosis." (PMID 39062119, 2024). "Moreover, MLKL ablation may, at least in part, influence glioma cell-cycle progression through effects on RIPK1." (PMID 41429922, 2025). "In both TCGA and CGGA cohorts, tumors with wild-type IDH exhibited higher expression of RIPK1, RIPK3, and MLKL relative to IDH-mutant gliomas, consistent with the more aggressive clinical behavior associated with IDH-wild-type status." (PMID 41429922, 2025). "In line with mRNA findings, RIPK1 and MLKL protein levels were higher in IDH-wild-type gliomas compared with IDH-mutant tumors." (PMID 41429922, 2025). "Analysis of The Cancer Genome Atlas (TCGA) and Genotype-Tissue Expression (GTEx) databases revealed a significant upregulation of RIPK1 and RIPK3 mRNAs in grade II–IV gliomas (G2–G4) compared with normal brain tissue." (PMID 41429922, 2025). "Similar findings were observed in the CGGA dataset, where RIPK1, RIPK3, and MLKL served as independent prognostic indicators across all WHO grades and within grade III gliomas." (PMID 41429922, 2025).